PMS2CL (PMS2 C-terminal like (pseudogene))
Synonyms: PMS2P13
Gene: Transcribed unprocessed pseudogene on chromosome 7 (6,735,305 to 6,751,392, forward strand). Ensembl gene ENSG00000187953.
Diseases named in the same sentence as PMS2CL in open-access papers:
PMS2CL is named in the same sentence as 5 diseases in open-access papers, as found by Europe PMC text mining. Sharing a sentence is not in itself a finding about the gene and the disease. The quoted sentences say what the papers report.
Lynch syndrome (2 papers, 2018 to 2026). An autosomal dominant hereditary neoplastic syndrome characterized by the development of colorectal carcinoma and a high risk of developing endometrial carcinoma, gastric carcinoma, ovarian carcinoma, renal pelvis carcinoma, and small intestinal carcinoma. "CNV detection in genes such as PMS2 (Lynch syndrome) and SMN1 (Spinal Muscular Atrophy) is notoriously challenging because of high-similarity paralogs (PMS2CL and SMN2) that cause nonspecific read alignment and distorted read depth." (PMID 41595524, 2026).
PMS2CL also shares sentences with these, for which no sentence is quoted: breast and (2 papers); cancer (1); ovarian carcinoma (1); spinal muscular atrophy (1).